BRD4 (bromodomain containing 4)
Diseases named in the same sentence as BRD4 in open-access papers (continued):
Sharing a sentence is not in itself a finding about the gene and the disease.
tumor (continued). "In this line, parameters such as cytotoxicity, tumor cell proliferation, viral replication, and interferon dependence of the oncolytic effect were investigated in six human tumor cell lines harboring the BRD4-NUT fusion oncoprotein." (PMID 35681742, 2022). "Our mRNA analysis showed that both the 80 and 150 kDa BRD4 isoforms were expressed in MLS tumour tissue." (PMID 35182012, 2022). "This substitution changes in structure and conformation of BRD4 results in the arbitration of oncogenic characters and leads to tumor genesis, metastasis, and tumor progression." (PMID 35401196, 2022). "The results showed that the expression of BRD4 was elevated in GC and its high expression in tumor tissues was shown to indicate poor prognosis in GC patients." (PMID 36352160, 2022). "This study provides pre‐clinical evidence for targeting BRD4 to augment anti‐tumour immunity of chemoradiotherapy and anti‐PD‐1 in NSCLC." (PMID 35083874, 2022). "The data showed that BRD4‐targeted therapy synergized with chemoradiotherapy and anti‐PD‐1 antibody by boosting anti‐tumour immunity in NSCLC." (PMID 35083874, 2022). "Then, previous studies showed that BRD4 is another key mediator of both tumour cell constitutive and IFN‐γ‐stimulated CD274 transcription." (PMID 35083874, 2022). "Immunohistochemistry (IHC) examination of the tumour sections showed that free ARV771 negligibly affected BRD4 expression." (PMID 35882867, 2022). "Specifically, immunoblot analysis after stimulation by hypoxia revealed a notable decrease in BRD4 level in multiple tumor cell lines with increasing concentration of the small-molecule substrates." (PMID 36516252, 2022). "By screening more than 2000 miRNA mimics, miR-1293, miR-876-3p, and miR-6571-5p were identified as tumor-suppressive miRNAs targeting BRD4." (PMID 35204785, 2022). "JQ1 induces progressive apoptosis of human carcinoma cells depending on Brd4 and exhibits anti-tumor effects." (PMID 36539410, 2022). "BRD4 restores anti-tumor immune responses following chemical inhibition with small-molecule bromodomain inhibitor JQ1, by down regulating PD-L1 expression in a MYC dependent manner in multiple myeloma." (PMID 36551637, 2022). "The majority of these cases manifested a tumor with chromosomal translocation, which forms the BRD4-NUT fusion oncogene (n = 16), BRD3-NUT (n = 4), NSD3-NUT (n = 3), NUT-variant (n = 1), CHRM5-NUTM1 (n = 1) and other NUTM1 rearrangements (n = 5)." (PMID 36290813, 2022). "Analysis of tissue microarray (TMA) from patients with NSCLC showed BRD4 protein expression is higher in tumour tissues compared with adjacent tissues." (PMID 35083874, 2022). "In AML, BRD4-facilitated transcription elongation repression is reduced due to mutation of cytoplasmic confined NPM1 gene, which results in overexpression of tumor progressive MYC gene along with BCL2 gene." (PMID 35401196, 2022). "BRD4 degradation-induced apoptosis of tumour cells in vivo was verified by haematoxylin-eosin (H&E) staining of the tumour sections." (PMID 35882867, 2022). "Since BRD4 is the utmost potential anti-tumour target, more than ten drugs targeting BRD4 have recently entered clinical trials." (PMID 36309482, 2022). "The abnormal expression of BRD4 is thought to be related to cell proliferation and poor outcomes in some tumor types." (PMID 36157053, 2022). "Previous studies found that miR-1293 inhibited the growth of tumor cells by simultaneously targeting BRD4, APEX1, RPA1, and POLD4 via inhibiting the DNA repair pathway." (PMID 36147635, 2022). "Immunohistochemical examination of the tumour tissue demonstrated significantly decreased BRD4 expression in vivo." (PMID 35882867, 2022). "The BRD4 inhibitor JQ-1 enhanced the anti-tumor activity of the mTOR inhibitor Palomid 529 in RCC cells." (PMID 35918352, 2022). "The specific binding of these inhibitors to BRD4, induces the displacement of BRD4 fusion from chromatin and leads to tumor regression in vivo." (PMID 36230614, 2022).
tumor (continued). "The enzyme activation-feedback epigenetic BRD4 protein degradation was further examined in different tumor cell lines including HeLa, MDA-MD-231, 4T1, and B16F10." (PMID 36516252, 2022). "Consistent with in vitro results, GNE987 administration (0.25 mg/kg) markedly decreased the tumor size in the xenograft model, with less toxicity, and induced similar BRD4 protein degradation to that observed in vitro." (PMID 35303940, 2022). "We focused on dasatinib, an approved multi-target kinase inhibitor with varied tumor-suppressive effects in GC cells and further studied the antitumor function of BRD4 inhibition in combination with dasatinib treatment in GC cells." (PMID 36352160, 2022). "The short isoform of BRD4 promotes tumor metastasis, and the long isoform of BRD4 inhibits tumor metastasis and spread." (PMID 36171897, 2022). "Regardless of the primary tumor and metastasis, the IHC score confirmed a remarkable increase of BRD4 expression in tumor tissues." (PMID 36352160, 2022). "In HCC, increased BRD4 expression is associated with higher mortality, which correlates with both MYC-dependent and MYC-independent tumor-promoting activity." (PMID 35399501, 2022). "Here, we report that PRMT2- and PRMT4-mediated arginine methylation is pivotal for BRD4 functions on transcription, DNA repair, and tumor growth." (PMID 36475791, 2022). "Our study showed that JQ1 inhibited the proliferation of three TNBC cell lines in vitro, and knockdown of BRD4 with shRNA in TNBC cell line MDA-MB-231 inhibited tumor growth in xenograft models." (PMID 36499487, 2022). "Further analysis showed that the expression of BRD4 was elevated nearly twofold in epithelial cells in tumoral and metastasis regions compared with normal regions, which implied a tumor-promoting function of BRD4 in GC." (PMID 36352160, 2022). "Previous studies have shown that the interaction between SIPA1 and several molecules is known to regulate cell proliferation and migration and can provide potential models for studying the process of tumor metastasis, such as BRD4." (PMID 36230738, 2022). "The tumor cell proliferation was significantly decreased in tumors from MDA-MB-231 cells with BRD4 shRNA compared with those from MDA-MB-231 cells with vehicle shRNA, as examined by Ki67 staining (p < 0.05, n = 3)." (PMID 36499487, 2022). "Simultaneous suppression of BRD4 and these DNA repair genes synergistically inhibited tumor cell growth." (PMID 35204785, 2022). "IRF1 is a well‐known transcription factor to regulate tumour cell PD‐L1 expression by binding to CD274 promoter, and BRD4 is another key mediator of both tumour cell constitutive and IFN‐γ‐stimulated CD274 transcription." (PMID 35083874, 2022). "The sensitivity of these tumour cells to BRD4 inhibition was recently attributed to a physical interaction between BRD4 and FET‐FOPs in MLS and EWS." (PMID 35182012, 2022). "Herein, we demonstrated the inhibition of BRD4 and consequently E6/E7 suppression by miR-9-5p which further strengthens its roles as a tumour suppressor in HPV-positive HNSCC." (PMID 36333293, 2022). "Here, we found that targeting BRD4 is one of the most promising methods to boost anti‐tumour immunity in combination with radiation and cisplatin as well as concurrent chemoradiotherapy via prohibiting the treatment‐induced PD‐L1 up‐regulation." (PMID 35083874, 2022). "We found that tumor xenografts formed by MDA-MB-231 cells with BRD4 shRNA were much smaller than those formed by MDA-MB-231 cells with vehicle shRNA after 4 weeks of inoculation (p < 0.05, n = 6)." (PMID 36499487, 2022). "An enzyme-derived clicking proteolysis targeting chimera degrades BRD4 specifically at the hypoxia settings within tumours." (PMID 36516252, 2022).
tumor (continued). "After 24 h of incubation, the GSH-activatable POLY-PROTACs of ARV771 and MZ1 efficiently degraded the BRD4 protein in MDA-MB-231 tumour cells in vitro." (PMID 35882867, 2022). "Following this, the targeting of wild-type BRD4 in hematological malignancies has likewise been shown to result in anti-tumor activity due to proto-oncogene downregulation." (PMID 36230614, 2022). "In 2015, Bradner’s group used JQ1 and thalidomide (a ligand for CRBN E3 ligase) to develop the BRD4-targeting PROTAC dBET1 with a DC50 value of 430 nM, attenuating tumor progression in vitro and in vivo by reducing the expression of BRD4 and c-myc." (PMID 35410300, 2022). "The mechanism of NMC is the function of the BRD4-NUT protein, which causes tumour cell proliferation and prevents cellular differentiation." (PMID 35832518, 2022). "Treatment with BET inhibitors (BETi) significantly reduced tumor growth and metastasis in both in vitro and in vivo models, and those effects were recapitulated by individual silencing of BRD4." (PMID 34575678, 2021). "Subsequent investigation found that miR-1293 suppresses tumor cell growth by targeting BRD4 and DNA repair genes at the same time." (PMID 34806748, 2021). "NHWD-870, a novel BRD4 inhibitor that suppresses the secretion of macrophage colony-stimulating factor (CSF)-1 by tumor cells and disrupts the BRD4/HIF-1α axis, is currently under preclinical investigation for the treatment of CM." (PMID 34575678, 2021). "In our previous studies, we explored the ability of a potent BRD4 inhibitor NHWD-870 shows great tumor suppressive potential in multiple solid tumors by depleting phosphorylated BRD4 and c-MYC." (PMID 34168981, 2021). "Another relevant issue is the fact that BRD4 is expressed in two major isoforms, short and long, that have been reported to play opposite functions as regulators of gene transcription and tumor progression." (PMID 33809005, 2021). "There are multiple transcriptional factors, such as MYC, EZH2, TRIM24, KLF4, and BRD4, that can regulate AR transcription by binding to its promoter in tumor cells." (PMID 34323404, 2021). "As to how HAT1 regulates AR expression, there are multiple transcriptional factors, such as MYC, EZH2, TRIM24, KLF4, and BRD4, regulate AR transcription by binding to its promoter in tumor cells." (PMID 34323404, 2021). "The inhibition of BRD4 reduces the levels of AR-driven target genes in PC, decreasing tumor burden in murine models." (PMID 34830196, 2021). "For instance, the simultaneous targeting of BRD4 (by BETi) and oncogenic pathways, such as WNT and MAPK, in CRC inhibits the oncogenic expression of MYC and decreases the risk of tumour resistance." (PMID 34298745, 2021). "Although there are many scenarios, it is possible that tumours that overexpress BRD4 depend on its expression for survival." (PMID 33723398, 2021). "I-BET151 was reported to impair tumor growth by displacing BRD4 from the chromatin, which reduced the expression of the Forkhead box protein M1 (FoxM1) transcription factor." (PMID 34758842, 2021). "This leads to an enrichment of super-enhancer marks H3K27ac and BRD4, and likely drives high expression of virus E6/E7 fusion transcripts with subsequent selection and neoplasia." (PMID 34432858, 2021). "Our study, however, provides a different mechanism by which the tumor microenvironment induces BRD4 stabilization through tyrosine phosphorylation at BD1 domain at Y97/98." (PMID 34290255, 2021).
tumor (continued). "We demonstrate a previously unrecognized tumor microenvironment mechanism by which paracrine IL6/IL8-JAK2 signaling induces BRD4 activation in CRC, leading to chromatin remodeling and resistance to BETi treatment." (PMID 34290255, 2021). "Inhibitors (such as JQ1) targeting BRD4 can target tumor-specific super enhancer-related genes in various kinds of tumors and suppress tumor proliferation and migration." (PMID 34733788, 2021). "NEO2734, a single agent targeting both BRD4 and p300, has shown a greater tumor suppression effect than single BET inhibitor treatment." (PMID 34898574, 2021). "Currently, more attention is being paid to the effect of Brd4 inhibition on tumor cell growth, while its effect on the function and differentiation of intratumor CD8+ T cells is spare." (PMID 34512660, 2021). "In our previous study, we reported the discovery and characterization of the novel BET inhibitor NHWD-870, and mechanism by which BRD4 inhibition suppresses tumor growth." (PMID 34168981, 2021). "Herein, we discovered the dual roles of methylated-BAF155 (me-BAF155) in promoting tumor metastasis: activation of super-enhancer-addicted oncogenes by recruiting BRD4, and repression of interferon α/γ pathway genes to suppress host immune response." (PMID 34865122, 2021). "Combinational treatment of mTOR (AZD8055) with either MEK (trametinib) or BRD4 (JQ1) inhibitors to EIF1AX-A113splice knock-in tumour cell lines result in reduced c-MYC and mTOR protein levels and consequent tumour size reduction." (PMID 34062862, 2021). "BRD4 overexpression has been shown to promote tumor growth by stimulating transcription of major oncogenic drivers, such as MYC." (PMID 32694708, 2020). "Increasing evidence suggests that BRD4 regulates many important genes and plays a critical role in tumor initiation, progression, and CSC maintenance." (PMID 32175692, 2020). "CD180, as well as CCR2, has been identified as robust pharmacodynamic tumor and blood biomarkers for clinical use with BRD4/BET inhibitors." (PMID 33082842, 2020). "BRD4 regulates MYC to promote tumor growth in many tumor types, and BET inhibition by JQ1 and its analog (FT1101, CPI‐0610, etc.)has shown activity in clinical trials (NCT02543879, NCT02158858, etc)." (PMID 32175692, 2020). "At the cellular level, the BRD4-c-Myc axis and the integrin-dependent pathways act cooperatively to drive tumor cell survival, growth and microenvironmental changes." (PMID 33006750, 2020). "Biological results showed that BRD4 functioned as tumor promoter, facilitated cell proliferation, migration and invasion in vitro and in vivo." (PMID 32099528, 2020). "To further understand the mechanisms by which BRD4 inhibition affected tumor growth, we examined the effects of NHWD-870 treatment on tumor microenvironment." (PMID 32286255, 2020). "Mechanistically, NHWD-870 reduces the expression and secretion of macrophage colony stimulating factor 1 (CSF1) in tumor cells by blocking the functional activity of BRD4 and its target gene HIF-1α." (PMID 33109235, 2020). "Migration and invasion were determined by Transwell assays, and the effect of BRD4 on subcutaneous tumor formation was verified in nude mice." (PMID 32099528, 2020). "Surprisingly, addition of exogenous TAMs was unable to rescue the strong effects of BRD4 inhibition on tumor cell proliferation and tumor growth (NHWD-870+TAM vs TAM and Ctrl)." (PMID 32286255, 2020). "Results showed that BRD4 protein levels were significantly increased in VS-5584-treated 786-O tumor tissues compared with those in vehicle control-treated tumor tissues." (PMID 33051401, 2020). "In the NB xenograft model, ARV-825 profoundly reduced tumor growth and led to the downregulation of BRD4 and MYCN expression in mice." (PMID 33324552, 2020). "Taken together, these results reveal a mechanism by which BRD4 inhibition suppresses tumor growth, and support further development of NHWD-870 to treat solid tumors." (PMID 32286255, 2020).
tumor (continued). "Recent studies have demonstrated that BRD4 plays an important role in tumor development and progression." (PMID 32099528, 2020). "Studies are in progress to optimize BETi + CHK1i combination therapy in the context of standard-of-care therapy, understand BRD4-dependent mechanisms of action, and study the tumor adaptive response over time." (PMID 32859084, 2020). "SRX3177 displayed greater tumor cytotoxicity as compared to the dual BRD4/PI3K inhibitor, SF2523 or dual BRD4/CDK4/6 inhibitor, SRX3177P." (PMID 32793389, 2020). "Together, these in vivo observations indicate that co-inhibition of FAK and the BRD4/c-Myc axis effectively suppresses tumor growth and immunity evasion-oriented microenvironments." (PMID 33006750, 2020). "Consistent with previous studies, we found that BRD4 was upregulated in RCC tumor samples and cell lines." (PMID 32303673, 2020). "A high level of BRD4 is found in super-enhancers of tumor cells, which are 15-fold larger and notably more active than typical enhancers." (PMID 32961679, 2020). "In summary, we provide strong evidence that inhibitors of LSD1 and BRD4 effectively inhibit tumor cell proliferation in high AR-expressing PCa tumors but also increase invasion in this population of PCa cells." (PMID 31901895, 2020). "Immunohistochemistry results demonstrated that the level of BRD4 and Ki-67 were suppressed by circCELSR1 knockdown, suggesting that circCELSR1 promoted BRD4 and tumor cell proliferation in vivo." (PMID 32640974, 2020). "A recent report demonstrated that BRD4 controlled tumor metastasis via stability and expression of Snail in breast cancer." (PMID 31908141, 2020). "The expression of the c-Myc gene is regulated by P-TEFb recruited by Brd4, and removal of Brd4 from the c-Myc locus by BETi results in a potent anti-tumor effect." (PMID 32075058, 2020). "Combined, these data indicate that repression of the BRD4/c-Myc axis promotes tumor cell dependence towards the integrin/FAK-mediated signaling pathways, suggesting a synthetic lethality-like effect of the JQ1/VS-6063 combination." (PMID 33006750, 2020). "The endogenous BRD4 mRNA levels in the LCM‐isolated tumour cells of 40 primary GISTs were quantified, revealing significant upregulation in higher risk categories defined by both the NCCN guidelines and the NIH scheme." (PMID 31957165, 2020). "Recently, BRD4 was shown to preferentially localize at the super-enhancers of a series of critical oncogenes, initiating and maintaining their expression in tumour cells." (PMID 31937753, 2020). "Several inhibitors of BRD4 proteins are being developed and many are in clinical trials for different tumor types." (PMID 33488950, 2020). "The putative interaction of BRD4 with P-TEFb seems therapeutically interesting, especially for a transcriptionally driven tumor such as EwS." (PMID 32012890, 2020). "And the forced expression of BRD4 was sufficient to promote tumor growth and epithelial-mesenchymal transition in HCC." (PMID 32927435, 2020). "The importance of this clinical association is underscored by a strong cooperation between FAK and the BRD4/c-Myc axis in driving tumor cell proliferation, survival and signaling via multiple pathways." (PMID 33006750, 2020). "Western blotting analyses showed that protein expression of BRD4, c-Myc, Bcl-2 and cyclin D1, were significantly decreased in A1874-treated tumor tissues, where caspase-3 and PARP cleavage was detected." (PMID 32978368, 2020). "The anti-tumor activity of the first-generation BET inhibitor JQ1 was first demonstrated in NUT midline carcinoma harboring a BRD4-NUT fusion gene." (PMID 33324552, 2020). "Biological results demonstrated that BRD4 functioned as tumor promoter, facilitated PC cell proliferation, migration and invasion in vitro and in vivo, consistent with previous research." (PMID 32099528, 2020). "Correlation analyses showed that the CSF1 levels correlated significantly with the p-BRD4 levels in tumor cells (r = 0.5122)." (PMID 32286255, 2020).